ZEB1 (zinc finger E-box binding homeobox 1)
Diseases named in the same sentence as ZEB1 in open-access papers (continued):
Sharing a sentence is not in itself a finding about the gene and the disease.
colorectal cancer (continued). "For example, evidence suggests that ZEB1 activates the H3K4me3 writer SETD1B in colorectal carcinoma, leading to a positive feedback loop of transcriptional potentiation of ZEB1 and thus EMT." (PMID 39095874, 2024). "The transcription inhibitor ZEB1 can inhibit the expression of miR-141 and members of the miR-200 family in colorectal cancer." (PMID 37465677, 2023). "Antioxidant response element-bound nuclear Nrf2 (nNrf2) promotes chemoresistance in colorectal cancer through the EMT pathway via the NF-κB/AKT/β-catenin/ZEB1 cascade by inducing PSMD4 expression." (PMID 37349676, 2023). "In colorectal cancer, miR-873-5p can target ZEB1 to inhibit the migration, invasion and EMT of cancer cells." (PMID 35582235, 2022). "HCP5 enhances epithelial-mesenchymal transition by activating ZEB1 and targeting miR-139-5p in colorectal cancer." (PMID 35602292, 2022). "The expression of several zinc finger proteins, such as ZEB1, ZFX and PRDM1, has been reported to be associated with the survival of colorectal cancer patients." (PMID 33892786, 2021). "Regarding activation of EMT-TFs, a previous study in colorectal cancer reported that ZEB1, one of the core EMT-TFs, was activated through the β-catenin/TCF4 complex." (PMID 34356119, 2021). "In colorectal cancer, HCP5 contributes to epithelial–mesenchymal transition in colorectal cancer through HCP5/miR-139-5p/ZEB1 axis." (PMID 34923990, 2021). "Meanwhile, USP43 can deubiquitinate and stabilize the ZEB1 protein, which plays an important role in the function of colorectal cancer." (PMID 33391437, 2021). "miR-186-5p overexpression can suppress the colorectal cancer cell proliferation, metastasis, and epithelial-to-mesenchymal transition by targeting ZEB1." (PMID 34804161, 2021). "For instance, STAT3 regulated zinc finger E-box-binding homeobox 1 (ZEB1) expression that decreased E-cadherin and increased N-cadherin/vimentin expressions, which promote metastasis in colorectal cancer." (PMID 33406733, 2021). "In this study, we found a synchronized transcript abundance of Snail and Zeb1 mediated by a non-coding RNA network in colorectal cancer (CRC)." (PMID 34502497, 2021). "It has been shown that PLAGL2 promoted EMT by USP37-mediated deubiquitination of Snail1 in gastric cancer, as well as β-catenin-dependent regulation of ZEB1 in colorectal cancer." (PMID 34944712, 2021). "For the first time we report that ZEB1 directly regulates the expression pattern of the histone methyltransferase SETD1B in colorectal cancer cells." (PMID 32094334, 2020). "The forkhead box K2 protein (FOXK2) promotes colorectal cancer metastasis by upregulating mRNA expression of zinc finger E-box binding homeobox 1 (ZEB1)." (PMID 32194639, 2020). "miR-101 functions as a tumor suppressor by directly targeting ZEB1 (zinc finger E-Box binding homeobox 1) in various cancers, including colorectal cancer." (PMID 31947678, 2020). "H19 acts in colorectal cancer as a microRNA sponge for MiR-138 and MiR-200, which then target zinc finger e-box binding homeobox 1 (ZEB1) and ZEB2 that are important mesenchymal cell markers in EMT." (PMID 33193379, 2020). "Zinc-finger E-box binding homeobox 1 (ZEB1) is another important inducible factor of EMT in many carcinoma cells including colorectal cancer." (PMID 32974136, 2020). "Collectively, our findings suggest that PLAGL2 mediates EMT to promote colorectal cancer metastasis via β-catenin-dependent regulation of ZEB1." (PMID 31827238, 2020).
colorectal cancer (continued). "A recent study demonstrated that IL-13 can induce an aggressive type of colorectal cancer by enhancing the expression of the epithelial–mesenchymal transition-promoting factor ZEB1 through the STAT6-dependent pathway." (PMID 33352852, 2020). "Expression of the EMT marker ZEB1 has previously been shown to be transcriptionally regulated by β-catenin/TCF protein complexes in colorectal cancer cells, and we found elevated ZEB1 in cells with mutant β-catenin." (PMID 30148686, 2019). "For instance, the overexpressed lncRNA XIST in colorectal cancer promoted cell proliferation and invasiveness through controlling ZEB1 expression by acting as a ceRNA for miR-200b-3p." (PMID 31998636, 2019). "In colorectal cancer, the lncRNA H19 was reported to derepress the endogenous genes, Vimentin, ZEB1, and ZEB2, by targeting miR138 and miR200a." (PMID 31752684, 2019). "Knock-down of ELF3 in HCT116 colorectal cancer cells substantially increased ZEB1 expression suggesting that ELF3 functions as a repressor of ZEB1 expression." (PMID 30148686, 2019). "In this study we identified ELF3 as a repressor of the EMT-TF and marker ZEB1 in colorectal cancer cells through its antagonism of Wnt and RAS oncogenic signalling pathways." (PMID 30148686, 2019). "There are two main complementary findings highlighted in this study: 1) a positive association between OGN and improved survival in primary CRC tumors; and 2) reduced activation of EGFR/AKT/Zeb-1 in colorectal cancer cells when OGN over-expressed." (PMID 29499765, 2018). "OGN plays a restrictive role in colorectal cancer progression by reduced activation of EGFR/AKT/Zeb-1." (PMID 29499765, 2018). "IDH1/2 mutations that induce the accumulation of 2-HG lead to EMT by ZEB1 upregulation and miR-200 downregulation in breast tumors and in colorectal cancer cells." (PMID 30671168, 2018). "ZEB1 silencing upregulates the expression of several polarity genes in colorectal carcinoma cells, including crumbs homolog 3 (CRB3) and lethal giant larvae 2 (LGL2)." (PMID 29258163, 2017). "In conclusion, ZEB1 promote VM formation by inducing EMT in colorectal carcinoma through the inhibition of VE-cadherin." (PMID 28320399, 2017). "A previous study identified ZEB1 as a key promoter of metastasis in pancreatic and colorectal cancer cells." (PMID 27818995, 2016). "This functional relationship between ZEB1 and miR-200c was further analyzed using a ZEB1 knockdown in breast and colorectal cancer cell lines." (PMID 27601996, 2016). "It has been reported that the overexpression of ZEB1 promoted the metastasis of colorectal cancer in a mouse xenograft model." (PMID 26423775, 2015). "Here, we show that in colorectal cancer cells endoplasmic reticulum-stress depends on the induction of ZEB-1, which is a main factor of epithelial-mesenchymal transition." (PMID 24498091, 2014). "miR-203 transcription is specifically repressed by the EMT activator Zeb-1, contributing to the invasive and metastatic behavior of pancreatic and colorectal cancer cells." (PMID 24520289, 2014). "In our study EMT was detected in samples of colorectal cancer based on coordinated changes in the expression of the following genes: ZEB1, ZEB2, SNAI1, CDH1, and VIM." (PMID 25157365, 2014). "Zinc finger E-box binding homeobox 1 (ZEB1) encodes a transcription factor that plays a key role in cancer progression by regulating EMT in breast, prostate, ovarian and colorectal cancer." (PMID 23420790, 2013). "Moreover, the promotion of ZEB1 expression in colorectal cancer cells by F. nucleatum was dependent on the ERK signaling pathway." (PMID 39757156, 2025). "Among these, ZEB1, SPARC, CDH1 and EpCAM were the most significantly differentially expressed genes between TRPS1-WT and TRPS1-MT cells and had been previously associated with colorectal cancer metastasis." (PMID 39307879, 2024).
colorectal cancer (continued). "Furthermore, the impact of USP43 on the susceptibility of colorectal cancer cells to chemotherapy, reveals a potential role for USP43 in upregulating ZEB1 expression and downregulating chemotherapy resistance in colorectal cancer." (PMID 38613804, 2024). "However, the overexpression of MEF2D has also been shown to induce the EMT in colorectal cancer, potentially through the transcriptional activation of ZEB1." (PMID 38791246, 2024). "Thus, ZEB1 can function as a tumor suppressor in BRAF-mutant colorectal cancer, which highlights the importance of analyzing the KRAS/BRAF mutational background in this disease." (PMID 38139138, 2023). "An earlier study showed that Claudin-1 could attenuate E-cadherin expression in colorectal cancer by upregulating ZEB-1, which, in turn, promoted EMT and reduced anoikis." (PMID 37350934, 2023). "ER stress in colorectal cancer cells is dependent on ZEB-1 induction." (PMID 36890838, 2023). "While ZEB1 was correlated with a worse prognosis and a higher number of larger and undifferentiated mesenchymal KRASG12D-colorectal carcinomas, it was associated with a better prognosis and fewer, smaller and more differentiated BRAFV600E primary colorectal tumors." (PMID 38139138, 2023). "Interfering with ZEB1 expression has been demonstrated to increase the sensitivity of colorectal cancer cells to chemotherapy, suggesting that reducing ZEB1 expression may help restore sensitivity in ZEB1-mediated chemotherapy resistance." (PMID 35897925, 2022). "In colorectal cancer, the hTERT/ZEB1 complex directly regulates E-cadherin to promote EMT." (PMID 35739589, 2022). "The COX‐2 selective antagonist celecoxib was revealed to prevent EMT‐mediated malignant transformation by modulating β‐catenin nuclear localization, the vimentin/E‐cadherin proportion and EMT‐TFs (Slug, Snail and ZEB1) in colorectal cancer cells and oral squamous cell carcinoma." (PMID 35601657, 2022). "TCGA and GTEx data indicated high PRAP1 expression and low ZEB1 expression in colorectal cancer." (PMID 35978266, 2022). "In line with an evidence in colorectal cancer identifying ZEB1 as a YAP/TEAD target gene, in this study we reveal the ability of ET-1 to activate both YAP and AP-1 pathways which, in turn, are involved in mediating the ET-1/ETAR axis transcriptional regulation of ZEB1." (PMID 35477522, 2022). "Additionally, miR-101 is downregulated in colorectal cancer tissues, lower expression of miR-101 results in overexpression of ZEB1, which promotes the migration of colorectal cancer cells." (PMID 36497343, 2022). "For example, in colorectal cancer with liver metastasis, miR-31-5p may inhibit and support EMT by upregulating c-MET, and the downregulation of miR-200 in colorectal cancer increases the expression of ZEB1, thereby promoting EMT." (PMID 36093435, 2022). "The heavy metal cadmium (Cd) can promote the migration and invasion of colorectal cancer cells, and Cd could upregulate the expressions of N-cadherin, vimentin, and ZEB1 and downregulate the expression of E-cadherin in colorectal cancer cells." (PMID 35784761, 2022). "SIX1 promotes EMT in colorectal cancer through ZEB1 activation." (PMID 35069900, 2022). "Evidence suggests that abnormal expression of ZEB1 may be involved in gastrointestinal (colorectal) cancer." (PMID 36204226, 2022). "Additionally, the m6A-induced lncRNA RP11 was identified as a new predictive biomarker that triggers the dissemination of colorectal cancer metastasis through upregulation of ZEB1." (PMID 35309906, 2022). "Interestingly, mutations in the Wnt signaling pathway are a major initiating event in colorectal cancer and regulate ZEB1 expression." (PMID 33768509, 2021). "In addition, we have studied the effect of USP43 and ZEB1 on chemotherapy sensitivity of colorectal cancer." (PMID 33391437, 2021). "Previously, PLAGL2 was validated to promote EMT process in colorectal cancer via regulating ZEB1." (PMID 34176471, 2021).
colorectal cancer (continued). "Although people have realized that ZEB1 may play an important role in tumor resistance, the specific mechanism of ZEB1 in colorectal cancer is still unclear and needs further research to clarify." (PMID 33391437, 2021). "In addition, ZEB1 expression level is higher in histone deacetylase inhibitor (HDACi) butyrate-resistant colorectal cancer cells." (PMID 33768509, 2021). "For example, circ_0026344 suppresses the metastasis of human colorectal cancer cells by sponging miR-18321, and the circRNA hsa_circ_0001178 facilitates the invasion and metastasis of colorectal cancer cells by sponging multiple miRNAs to upregulate ZEB1 expression." (PMID 33762580, 2021). "Exploring the hypothesis that Snail and Zeb1 show accordant transcript abundance, we chose HCT116, a colorectal cancer cell line with high expression levels of Snail and Zeb1." (PMID 34502497, 2021). "USP43 could promote cell proliferation, invasion, and migration in colorectal cancer by regulating ZEB1 ubiquitylation degradation." (PMID 33391437, 2021). "In addition, Prdx2 inhibited EMT in a colorectal cancer model, reducing invasive characteristics, via Twist1, Snail, ZEB1, and ZEB2." (PMID 33182509, 2020). "Previous studies found that miR-574 negatively regulated Qki6/7 to increase the proliferation, migration and invasion of colorectal cancer, while Wang and colleagues proved that miR-574 suppressed lung metastasis of triple-negative breast cancer by targeting ZEB1." (PMID 32381753, 2020). "Earlier studies showed that KCNQ1OT1 promoted NSCLC progression by modulating miRNA-27b-3p/HSP90AA1 axis, and stimulated cholangiocarcinoma development via miR-140-5p/SOX4 axis, and facilitated the migration and EMT of colorectal cancer by forming a feedback loop with miR-217 and ZEB1." (PMID 32821247, 2020). "In colorectal cancer cells, D-2HG (but not its enantiomer L-2HG, produced from the reduction of α-KG by lactate dehydrogenase A, LDHA, or malate dehydrogenase, MDH) directly induces EMT in colorectal cancer cells by promoting H3K4me3 marks at the ZEB1 promoter and its transcription." (PMID 31277295, 2019). "In addition, HIF-1α promotes EMT and cancer metastasis by binding to the promoter of ZEB1 in colorectal cancer." (PMID 30671168, 2018). "In breast and colorectal cancer ZEB1 is able to impact cell-cell adhesion and epithelial differentiation via key genes including the cell polarity genes HUGL2, Crumbs3 and PATJ (Pals1-associated tight junction) by binding to their promoters and repressing their transcription." (PMID 32309604, 2018). "Moreover, high levels of d-2HG induce an EMT-like phenotype via direct upregulation of ZEB1 expression by promoting the H3K4 trimethylation of the promoter region of ZEB1 in colorectal cancer cells." (PMID 29534029, 2018). "Our findings presented here provide evidence that carfilzomib may overcome the 5-FU resistance in colorectal cancer induced by the NF-κB/β-catenin/ZEB1 activation that is mediated by cNrf2-induced PSMD4 expression." (PMID 29899863, 2018). "In colorectal cancer H19 interacts with miR-200a and miR138 to boost Vimentin and ZEB1 expression." (PMID 28327666, 2017). "Similarly, it has been shown that colorectal carcinoma patients have elevated expression of mesenchymal marker including Snail and Zeb1." (PMID 28186986, 2017). "miR-200 suppression in poor prognosis of some colorectal cancer (CRC) cells may promote ZEB1-mediated cancer metastasis." (PMID 27285757, 2016). "Xiong found that STAT3 down-regulated E-Cadherin expression via ZEB1 in colorectal cancer cells." (PMID 25947346, 2015). "ZEB1 represses differentiation and cell–cell adhesion in human colorectal carcinoma cells." (PMID 19568234, 2009). "Therefore, NEAT1 could promote ZEB1 expression by targeting and inhibiting miR-448 and promote colorectal cancer proliferation and invasion in this way." (PMID 39830506, 2024).
colorectal cancer (continued). "Furthermore, NETs have been demonstrated to enhance migratory ability of human BC cells in vitro by altering the mesenchymal phenotype of the cells and to increase motility in colorectal cancer cells potentially by alterations in the expression of ZEB1, Slug and E-Cadherin." (PMID 38430241, 2024). "Besides, PLAGL2 might promote epithelial-mesenchymal transition and increase metastasis via β-catenin-dependent regulation of ZEB1 in colorectal cancer." (PMID 36879254, 2023). "It is worth noting that there have been no studies of epigenetic alterations of the FRMD6 and ZEB1 genes, which encode the proteins included in the panel, that are differentially expressed in colorectal cancer, as is demonstrated in Human Protein Atlas database." (PMID 38093305, 2023). "Similarly, by targeting ZEB1/2, MiR-144-3p suppressed colorectal cancer growth and metastasis." (PMID 35501800, 2022). "Therefore, our results revealed that USP43 and ZEB1 can regulate EMT of colorectal cancer." (PMID 33391437, 2021). "It was reported that ZEB1, as a key transcription factor, could bind the promoter region of hsa_circ_0001178 and increase its expression in colorectal cancer; similar studies that explore the upstream trigger of alternative splicing, which generate aberrant circRNAs, are needed in OSCC." (PMID 34510785, 2021). "Moreover, GRHL2 knockdown in colorectal cancer cells inhibits cell proliferation by targeting ZEB1." (PMID 32571262, 2020). "HIF-1α could bind directly to the proximal promoter of ZEB1 via HRE in colorectal cancer cells." (PMID 32322559, 2020). "Furthermore, ZEB1 directly represses the MIR200C/MIR141 locus in colorectal cancer cells." (PMID 32005677, 2020). "ZEB1 belongs to the EMT-TFs, and in colorectal cancer (CRC), a strong correlation between the cancer expression of ZEB1 and the number of CTCs detected in the blood of patients has been demonstrated." (PMID 40332096, 2025). "DHA has been shown to suppress expression of EMT-related genes including SNAIL, SLUG, ZEB1, and ZEB2 in colorectal cancer cells, resulting in decreased expression of N-cadherin and vimentin, increased E-cadherin expression, and reduced cell migration." (PMID 41009329, 2025). "Recently, astaxanthin has been reported to increase the expression of miR-29a-3p and miR-200a in colorectal cancer, thereby targeting MMP2 and ZEB1 and eventually inhibiting the epithelial-mesenchymal transition of cancer cells." (PMID 38649975, 2024). "Similar results were obtained in a model of colorectal cancer where sunitinib induces EMT with downregulation of E-cadherin and upregulation of Slug and Zeb1 in favor of tumoral progression." (PMID 38201462, 2023). "On the contrary, ZEB1/2 and Snail have also been identified as ESE1 transcriptional targets of repression in biliary tract and colorectal cancer." (PMID 36329620, 2023). "This is supported by the fact that β‐catenin/TCF4 can bind to the promoter of ZEB1 and increase its transcription, leading to the EMT and metastasis of colorectal cancer." (PMID 35601657, 2022). "In turn, the increased miR-29a-3p and miR-200a resulted in the reduced expression of MMP2 and zinc finger E-box binding homeobox 1 (ZEB1), which mediate the epithelial-mesenchymal transition of colorectal cancer cells." (PMID 36555112, 2022). "Hsa-miR-205-5p was also investigated by our team in colorectal cancer and showed its regulator role on the EMT pathway by modulation of ZEB1 and E-cadherin expression." (PMID 35628157, 2022). "Verbascoside adversely affects HIF-1α expression under normoxic conditions in colorectal cancer and downregulates EMT-related factors such as zinc finger E-box-binding homeobox 1 (ZEB1)." (PMID 34575983, 2021). "It’s worth to investigate the targets of ZEB1 regulating by cooperation of METTL14, YHTDF2, ARRDC4, TCF4 and HuR leads to elevation of invasiveness and migration of colorectal cancer cells in the future study." (PMID 34916487, 2021).